TREM2 (triggering receptor expressed on myeloid cells 2)
Diseases named in the same sentence as TREM2 in open-access papers (continued):
Sharing a sentence is not in itself a finding about the gene and the disease.
Alzheimer disease (continued). "Microglia play a pivotal role in recognizing amyloid β as a DAMP and triggering innate immune signaling, and although reactive astrocytes contribute to the inflammatory milieu, genetic risk factors such as TREM2 and CD33 variants implicate microglia as key players in Alzheimer's disease." (PMID 40064497, 2025). "TREM2’s role in Alzheimer’s disease (AD)/spinal cord injury (SCI) and AI-assisted opportunities." (PMID 41280332, 2025). "Besides TREM2 and the MS4A genes, variants of numerous additional genes increase late-onset Alzheimer’s disease risk and several of them are selectively expressed in microglia." (PMID 40081988, 2025). "Although research on Alzheimer’s disease (AD) revealed that microglial triggering receptor expressed on myeloid cells 2 (TREM2) plays a critical role in inhibiting neuroinflammation and improving cognition, its contribution to cognitive impairment following spinal cord injury (SCI) is unclear." (PMID 41280332, 2025). "Other highly cited articles predominantly discuss the role of neuroinflammation in various neurocognitive disorders, including Alzheimer’s disease, addressing immune activation, neuroinflammatory mechanisms, TREM2, NLRP3, cognitive impairment, and their relationship with disease progression." (PMID 40791247, 2025). "ZEB2 has not previously been implicated in TREM2 regulation or in neurodegenerative diseases such as Alzheimer’s disease." (PMID 41300781, 2025). "However, they predominantly focused on Alzheimer's disease (AD), with few studies examining TREM2 in ASD." (PMID 41476737, 2025). "During Alzheimer’s disease (AD) progression, the TREM2-TYROBP complex is involved in regulating the activation of DAM, that expresses high levels of phagocytic and lipid metabolism-related genes, suggesting its potential role in clearing amyloid-β (Aβ) plaques." (PMID 40242752, 2025). "Targeting TREM2 has emerged as a therapeutic approach to the treatment of Alzheimer’s disease." (PMID 39531316, 2024). "TREM2 has been intensively studied in the context of neurodegenerative diseases, revealing its concurrent role in engulfment of Aβ-amyloid plaques and sustainment of cellular energetic and biosynthetic metabolism during Alzheimer’s disease." (PMID 38182899, 2024). "Because of its control over microglial phagocytosis, TREM2 may play a protective role, though it may be involved differently in diseases like Alzheimer’s disease." (PMID 39544929, 2024). "Finally, this work has provided the first evidence of the important role Trem2 in fracture healing and demonstrated the need to focus future research on Trem2 in age‐related disease outside of Alzheimer's disease and related dementias." (PMID 38825965, 2024). "TREM2 is a transmembrane receptor exclusively expressed in the brain in microglia, acting as an extracellular lipid sensor that enhances microglia activity and is involved in neurological disorders like Alzheimer’s disease (AD)." (PMID 39456170, 2024). "If TREM2 dysfunction occurs, it may alter the response of microglia to βA and may be involved in the etiology of Alzheimer’s disease through immune and inflammatory pathways." (PMID 38419953, 2024). "All in all, the protein interaction partners determined in this computational study for alternatively spliced TREM2 isoforms suggest possible new functions of TREM2 isoforms with respect to Alzheimer’s disease, including the role of TREM2 isoform in cell adhesion and calcium signaling." (PMID 39273614, 2024). "Study of miRNA involvement in Alzheimer’s disease pathogenesis is relevant, since the associations of protein-coding genes (APOE4, ABCA7, BIN1, CLU, CR1, PICALM, TREM2) with the disease revealed as a result of GWAS make it difficult to explain its complex pathogenesis." (PMID 38680184, 2024).
Alzheimer disease (continued). "This binding may be similar to what has been described in the context of Alzheimer’s disease, where TREM2 in microglia binds to amyloid-β–lipoprotein complexes via APOE, thereby preventing amyloid-β accumulation." (PMID 36766683, 2023). "For example, an Alzheimer’s disease variant in the TREM2 gene (rs75932628) was also correlated with amyotrophic lateral sclerosis, while a variant in the MARK2 gene (rs10792421) was associated with Alzheimer’s disease and bipolar disorder." (PMID 36873109, 2023). "Future research in TREM2 p.R47H carriers with Alzheimer’s disease could address this but would be challenging due to the rarity of the variant." (PMID 37990275, 2023). "Importantly, both Trem2 agonistic and blocking antibodies have been developed for use in Alzheimer’s disease and cancer." (PMID 38646596, 2023). "This is in keeping with preclinical studies which have shown lower levels of hippocampal microglial activation in mice carrying the human TREM2 p.R47H variant, with or without Alzheimer’s disease pathology." (PMID 37990275, 2023). "In this review, we focus on the role of cells (microglia, astrocytes, and oligodendrocytes) and molecules (TREM2, tau, and β-amyloid) of the innate immune system in the pathogenesis of Alzheimer’s disease and their possible exploitation as disease biomarkers and targets of therapeutical approaches." (PMID 37569296, 2023). "TREM2/sTREM2 sustain cellular energetic and biosynthetic metabolism and then promote microglial responses during Alzheimer's disease, which maintains microglial metabolic fitness in Alzheimer's disease." (PMID 37435171, 2023). "TREM2, one of the most highly expressed receptors on microglia, is regarded as an important player in the transition of microglia from homeostatic to pathological state in the development of Alzheimer’s disease." (PMID 37457817, 2023). "Gene mutations affecting the expression and sequence of microglial genes (e.g. TREM2, CD33, and MS4A) increase risk for Alzheimer’s disease (AD), and implicate microglia in several disease pathways including toxic protein aggregation (Aβ and tau) and neuroinflammation." (PMID 36624100, 2023). "The role of TREM2 in Alzheimer’s disease (AD) is not fully understood." (PMID 37371067, 2023). "Apart from the “Total 17 NAbs” cluster, the NAb clusters for “Alzheimer’s disease” (SORL1, ADAM10, CLU and TREM2) and “Neurodegenerative disease” (SORL1, ADAM10, CLU and TREM2 and WWOX) showed the best diagnostic performance for AD with sensitivity (against 95% specificity) up to 0.759." (PMID 36922858, 2023). "In addition, two sequential pro-inflammatory stages of DAM have been characterized in murine models of Alzheimer’s disease, according to the sequential up-regulation of the TREM2-ApoE pathway." (PMID 35663580, 2022). "In addition, VTN has been reported to be related with TREM2 in patients with Alzheimer’s disease, which is an important gene for maintaining MG metabolism." (PMID 36293243, 2022). "TREM2 has primarily been recognized for its expression on cells in the monocyte-macrophage lineage, with the majority of work focusing on microglial function in Alzheimer’s Disease." (PMID 36119485, 2022). "TREM2 promotes the optimal microglial function required to attenuate disease progression and is a potential target for eliciting a protective role of microglia in Alzheimer’s disease and other neurodegenerative diseases." (PMID 35359989, 2022). "As the infection progresses, we noted an enrichment for genes associated with neurodegenerative disorders (e.g., Amyotrophic lateral sclerosis, Huntington disease, Parkinson disease, and Alzheimer’s disease) such as Apoe, Trem2, and Psen2 (Fig. 3Hleft, Supplementary Datas 9 and 10)." (PMID 36180478, 2022).
Alzheimer disease (continued). "While there are no current therapies in preclinical or clinical trials targeting TREM2 in the context of TB, AL002, a humanized monoclonal TREM2 antibody currently in a phase 2 clinical trial, has been reported to be a promising candidate for Alzheimer’s disease therapy." (PMID 35924849, 2022). "Moreover, an imbalance in the TREM2/TLR4 ratio has been reported to have detrimental effects regarding neuroinflammation in Alzheimer Disease." (PMID 36293468, 2022). "In the present review, we scrutinize different interactions and important factors including direct cell–cell contact, intervention by the CD200 system, various receptors present on their surfaces, CXC3RI and TREM2, and chemokines and cytokines with special reference to Alzheimer’s disease (AD)." (PMID 35053818, 2022). "Emerging evidence has suggested that abnormal TREM2 expression and signaling within the brain may promote progressive dementia, such as Alzheimer’s disease and Nasu–Hokola disease, which is a genetic disorder characterized by early-onset dementia." (PMID 34838047, 2021). "During Alzheimer disease (AD), disease-associated microglia (DAM) and late-response microglia are defined by the expression of genes related to lipid metabolism and phagocytosis (ApoE, Lpl, Trem2, Tyrobp, Ctsd) and interferon response." (PMID 34540682, 2021). "TREM2 in particular has been extensively studied in mouse and induced pluripotent stem cell (iPSC) models, mainly due to its link to microglial involvement in Alzheimer's disease pathology." (PMID 34282843, 2021). "TREM2 has been shown to play a significant role in Alzheimer's disease." (PMID 34354664, 2021). "Targeting TREM2-APOE signaling eliminated pro-inflammatory macrophages (Ly6C+) in Alzheimer's disease mice, restored the homeostatic signature of microglia, reduced inflammation, ameliorated Aβ deposition and Tau pathology, and prevented neuronal death in an acute model of neurodegeneration 36,52." (PMID 34815787, 2021). "Importantly, variants of the TREM2 and CD33 genes are risk factors for Alzheimer’s disease (AD), probably due to impaired uptake and clearance of amyloid-β (Aβ)." (PMID 33758958, 2021). "Using NEBULA in Alzheimer’s disease cohort data sets, we found that the cell-level expression of APOE correlated with that of other genetic risk factors (including CLU, CST3, TREM2, C1q, and ITM2B) in a cell-type-specific pattern and an isoform-dependent manner in microglia." (PMID 34040149, 2021). "Interestingly, PU.1, which was proposed to be a key transcription factor for regulating TMEM119 expression, also acts as an upstream regulator of TREM2, suggesting a functional role of TMEM119 in the pathological changes associated with Alzheimer’s disease." (PMID 34571885, 2021). "Furthermore, evidence of stage 1 (TREM2 independent) and stage 2 (TREM2 dependent) disease-associated microglia (DAM) transcriptional signatures as described for Alzheimer disease models, start to be evident as early as 3 months in Tpp1−/− brains." (PMID 34749772, 2021). "It appears that either TREM2 or sTREM2 are protective in Alzheimer's disease, but which?" (PMID 35153729, 2021). "Moreover, in a mouse model for Alzheimer's disease‐related pathology, 4D9 reduced amyloidogenesis, enhanced microglial TREM2 expression, and reduced a homeostatic marker, suggesting a protective function by driving microglia toward a disease‐associated state." (PMID 32154671, 2020). "Neuroinflammation has emerged as a targetable mechanism in Alzheimer’s disease (AD) over the last ten years, which has been driven by GWAS (Genome Wide Association Studies) signals in several genes (CR1, CLU, TREM2, HLA-DRB5/DRB1, INPP5D, and MEF2C) that are implicated in inflammation." (PMID 33352944, 2020).
Alzheimer disease (continued). "Triggering receptor expressed on myeloid cells 2 (TREM2) is expressed in the brain exclusively on microglia and genetic variants are linked to neurodegenerative diseases including Alzheimer’s disease (AD), frontotemporal dementia (FTD) and Nasu Hakola Disease (NHD)." (PMID 33115519, 2020). "Recently, TREM2 has been found to play a role in the development of Alzheimer’s disease (AD)." (PMID 32635934, 2020). "A cross-sectional study of 1027 participants of the Alzheimer’s Disease Imaging Initiative (ADNI) cohort, including 43 subjects carrying TREM2 rare genetic variants, was conducted to measure CSF sTREM2 using a previously validated enzyme-linked immunosorbent assay (ELISA)." (PMID 30630532, 2019). "Furthermore, the association of immune receptors, including TREM2 and CD33 with Alzheimer’s disease, indicate the important part neuroinflammation played in this disease." (PMID 30696107, 2019). "MerTK+/Axl+ macrophages surrounding plaques in mouse models of Alzheimer disease express TREM2." (PMID 31614590, 2019). "This reveals not only changes in expression of the gene for the phagocytic protein CD68, tested with immunohistochemistry in the present study but also even greater changes in Trem2 expression, a gene shown in humans to be important in Alzheimer's disease in GWAS." (PMID 30555043, 2019). "Both hetero- and homozygous TREM2 knock-out MGLs exhibited a reduced capacity to phagocyte E. coli fragments in vitro and amyloid plaques in cocultures with brain cryosections derived from a mouse model of Alzheimer’s disease." (PMID 31856864, 2019). "TYROBP/DAP12 forms complexes with ectodomains of immune receptors (TREM2, SIRPβ1, CR3) associated with Alzheimer’s disease (AD) and is a network hub and driver in the complement subnetwork identified by multi-scale gene network studies of postmortem human AD brain." (PMID 30283031, 2019). "Next generation sequencing of a panel of 17 genes associated with different forms of dementia revealed a TREM2 R62H variant, a risk factor for Alzheimer’s disease, but no other alterations." (PMID 29450646, 2018). "Finally, the scavenger receptor TREM2 has been recently identified as an ADAM10 substrate with a potential role in Alzheimer’s disease." (PMID 30013551, 2018). "Overexpression of TREM2 in an Alzheimer’s disease transgenic mouse model significantly ameliorates Alzheimer’s disease-related neuropathology, including Aβ deposition, neuroinflammation, and synaptic losses, which is accompanied by improved spatial cognitive functions." (PMID 28592261, 2017). "The balance of delivery and proteolytic shedding of TREM2 from the cell surface may have a role in the neuroinflammatory pathogenesis of Alzheimer's disease." (PMID 28855301, 2017). "In Alzheimer’s disease levels of soluble TREM2 are higher in early phase disease." (PMID 28302159, 2017). "Sequence variations occurring in the gene encoding the triggering receptor expressed on myeloid cells 2 (TREM2) support an essential function of microglia and innate immunity in the pathogenesis of Alzheimer's disease (AD) and other neurodegenerative disorders." (PMID 28855300, 2017). "Triggering receptor expressed on myeloid cells 2 (TREM2) is a microglia-specific receptor and could decrease neuropathology in Alzheimer's disease (AD)." (PMID 29180839, 2017). "Furthermore, both TREM2 and DAP12 mutations have been found to be associated with the risk for Alzheimer’s disease (AD)." (PMID 28680398, 2017). "Mutations of TREM2 cause skeletal and psychotic abnormalities called Nasu-Hakola disease (NHD), or a neurodegenerative disorder characterized by numerous deficits in neurotransmitter function called Alzheimer's disease." (PMID 26506595, 2016).
Alzheimer disease (continued). "Additionally, it can upregulate pro-inflammatory microRNAs (such as miRNA-34a and miRNA-146a), which can downregulate the expression of triggering receptors expressed on myeloid cells 2 (TREM2), thereby exacerbating neuroinflammation and Alzheimer’s disease pathology." (PMID 41356558, 2025). "In Alzheimer's disease, the imperative to foster phagocytosis while mitigating inflammation emerges; however, the anti-inflammatory signaling of TREM2 may inadvertently disrupt the body's intrinsic anti-tumor defenses or exacerbate pro-fibrotic responses in the aftermath of liver injury." (PMID 40552184, 2025). "Interestingly, TREM2 is upregulated in DAM and microglia associated with neurodegeneration, but not in LDAM (lipid droplet-accumulating microglia), which are thought to be associated with aging and Alzheimer’s Disease." (PMID 41333389, 2025). "Notably, several Alzheimer’s disease (AD)-associated genetic risk variants—including APOE ε4, TREM2 R47H (rs75932628), CD33 rs3865444-C, INPP5D regulatory variants, MS4A6A locus variants, and PLCG2 P522R (rs72824905)—are enriched in microglia and influence their functional state." (PMID 40934003, 2025). "Moreover, TREM2 agonists is undergoing phase III clinical trials in Alzheimer’s disease." (PMID 38182899, 2024). "Therefore, we speculate that AS and Alzheimer’s disease may have similar TREM2 signaling regulatory mechanisms." (PMID 36552740, 2022). "Prominently, in rodent models of neurodegenerative diseases including the Alzheimer’s disease (AD) and Amyotrophic lateral sclerosis (ALS), microglia display a stereotypic disease-associated microglia (DAM) phenotype, which appears to be an inflammatory state driven by a TREM2-dependent pathway." (PMID 36591296, 2022). "Interestingly, the transcriptomic approach on ex vivo brain tissue from a murine model of Alzheimer’s disease recently led to characterization of a novel phenotype of activated microglia, distinct from Trem2-ApoE-Clec7a-expressing DAM, but still increasing (as DAM) along disease progression." (PMID 35663580, 2022). "Indeed, microglia lacking TREM2 expression exhibit greatly diminished activation against disease pathology, correlating with increased risk of Alzheimer’s disease (AD)." (PMID 35191835, 2022). "Therefore, a compromised function of TREM2 may lead to decreased clearance of cell debris and possibly the removal of Aβ in Alzheimer’s disease." (PMID 33806317, 2021). "DAM markers Apoe and Trem2 were similarly increased, and Gpnmb, which has also been identified in the brains of mouse models of Gaucher disease as well as in patients after developing Alzheimer’s disease, was increased several 1000-fold in the spinal cord of twitcher." (PMID 34172992, 2021). "Since microglia are the central immune cells of the CNS and TREM2 has been already related to Alzheimer’s disease, frontotemporal lobar degeneration, Parkinson’s disease, and others, it is questioned whether this receptor is also involved in prion disorders, like CJD." (PMID 34751640, 2021). "Generating TREM2 mutation hPSCs using CRISPR/Cas9 in human microglia-like cells, demonstrated TREM2 expression related to amyloid plaque metabolism, which might advance the current understanding regarding Alzheimer's disease (AD)." (PMID 34887928, 2021). "Here, we report the generation and characterization of a model of late-onset Alzheimer’s disease (LOAD) using lymphoblast-derived induced pluripotent stem cells (iPSCs) from patients carrying the TREM2 R47H mutation, as well as from control individuals without dementia." (PMID 32630447, 2020). "This study describes the discovery and characterization of a novel TREM2 antibody, which induces protective microglial functions and provides a basis for the development of human antibodies with a similar mechanistic profile for treatment of Alzheimer's disease." (PMID 32154671, 2020).